LMO1 (LIM domain only 1)
Diseases named in the same sentence as LMO1 in open-access papers (continued):
Sharing a sentence is not in itself a finding about the gene and the disease.
neuroblastoma (continued). "Here, we show for the first time that in neuroblastoma, iron chelator VLX600 inhibits mitochondrial respiration, decreases expression levels of MYCN/LMO1, and induces an efficient cell death regardless of MYCN status in both 2D and 3D culture conditions." (PMID 35805002, 2022). "A recent study reported that transgenic expression of LMO1 alone failed to induce tumorigenesis in a zebra fish model, but acted as a synergist of MYCN, an oncogene amplified in ~20% of neuroblastoma." (PMID 30406033, 2018). "Here, in this paper, we for the first time show that the iron chelator VLX600 inhibits mitochondrial respiration, decreases mTOR activity, reduces the expression of MYCN/LMO1 and induces an efficient cell death regardless of MYCN statues in neuroblastoma cells." (PMID 35805002, 2022). "Because neither lmo1–/– nor TATA/TATAMYCN–expressing tumors appeared to be driven by the adrenergic CRC, which is preferred by neuroblastomas arising in the GATA/GATA background, we questioned whether either tumor type was instead driven by the mesenchymal CRC." (PMID 37183825, 2023).
leukemia (16 papers, 2013 to 2025). A malignant (clonal) hematologic disorder, involving hematopoietic stem cells and characterized by the presence of primitive or atypical myeloid or lymphoid cells in the bone marrow and the blood. "TAL1 is a master oncogenic driver in a major subset of T-ALL, and LMO1 is a frequent cofactor in TAL1-driven leukemias." (PMID 41007654, 2025). "In leukemia, Olig2 seems only oncogenic in thymocytes and collaborative with LMO1 and Notch1 to induce highly penetrant leukemia." (PMID 36990974, 2023). "Expression of Lmo2 accelerates the onset of leukemia in Tal1 transgenic mice, and LMO1/LMO2 are commonly expressed in human TAL1-driven T-ALL." (PMID 34501239, 2021). "Since then, the role of LMO1 in the development of leukemias and lymphomas has been characterized in vivo in mouse models." (PMID 30038707, 2018). "TAL1s is sufficient to induce leukemia in combination with another E-box transcription factor (Lim domain only 1) LMO1." (PMID 28545085, 2017). "Tal1 and Lmo1/2 transgenic mice show an increased number of thymic progenitors that can generate leukemia, indicating that these oncogenic transcription factors are capable of inducing LIC ability in immature thymocytes." (PMID 29034206, 2017). "Overexpression of LMO1 or LMO2 in the thymus induces leukemia in mice with low penetrance and long latency." (PMID 25522233, 2014). "Interestingly, upregulation of Olig2 alone is weakly oncogenic in leukemia, however, together with LMO1 and Notch1, overexpression results in cell proliferation." (PMID 37274223, 2023). "Given that LMO1 expression is minimal in normal blood cells but can be substantial in a subset of T-ALL leukaemia patients, we next investigated whether the LMO1 promoters and +57 enhancer element showed activity in T-ALL cells." (PMID 23302769, 2013). "Therefore, SCL and LMO1 acting in synergy with two essential signaling pathways in thymocyte development are sufficient to transform a normal DN3a thymocyte into a fully transformed leukemia initiating cell." (PMID 35401501, 2022). "We previously showed that these pre-LSCs are driven by the SCL/TAL1 and LMO1 oncogenes, which depend on NOTCH1-MYC pathways, and are resistant to chemotherapeutic drugs used against leukemia (doxorubicin, camptothecin and dexamethasone)." (PMID 31196146, 2019). "By quantifying two disease endpoints, T-ALL penetrance and disease latency, i.e. the median time to overt leukemia, we show that in the context of the SCL and LMO1 oncogenes, the hyperactive Notch1 oncogene on its own determines disease penetrance even in the absence of pre-TCR signaling." (PMID 35401501, 2022). "Despite a clear role in leukaemia, there is no significant LMO1 expression at major stages of normal haematopoietic differentiation." (PMID 23302769, 2013).
acute lymphoblastic leukemia (13 papers, 2013 to 2025). Leukemia with an acute onset, characterized by the presence of lymphoblasts in the bone marrow and the peripheral blood. "Interestingly, ALDH1a2 RNA amplification is necessary for LMO1-fusion T cell acute lymphoblastic leukemia (T-ALL) transformation, showing that atRA has unique autocrine cancer effects in this specific T cell leukemia." (PMID 39133222, 2024). "LMO1 is a transcriptional regulator and a T-acute lymphoblastic leukaemia (T-ALL) oncogene." (PMID 23302769, 2013). "Deregulated expression of LMO1 may be involved in the development and maintenance of T‐ALL (T‐acute lymphoblastic leukaemia)." (PMID 31830377, 2020). "Mice, bearing human oncogenes TAL BHLH Transcription Factor 1 (TAL1; SCL) or LIM Domain Only 1 (LMO1), responsible for T-cell acute lymphoblastic leukemia (T-ALL) development, were crossed with BCL11B floxed and with CRE-ER/lox mice." (PMID 35563322, 2022). "LMO1 and LMO2 are oncogenes that are recurrently translocated and overexpressed in T-cell acute lymphoblastic leukemia (T-ALL)." (PMID 32195177, 2020).
T-cell acute lymphoblastic leukemia (11 papers, 2006 to 2025). Acute lymphoblastic leukemia of T-cell origin. "For example, non-coding mutation hotspots upstream of TAL1 and LMO1 in T-cell acute lymphoblastic leukemia lead to the formation of de novo MYB binding sites that drives the overexpression of TAL1 and LMO1 oncogenes." (PMID 32550006, 2020). "Lmo1 encodes a transcriptional regulator, and it has been reported that overexpression of LMO1 inhibits T cell differentiation and induces aggressive T cell acute lymphoblastic leukemia." (PMID 33644036, 2020). "Here we report a C-to-T single nucleotide transition that occurs as a somatic mutation in noncoding sequences 4 kb upstream of the transcriptional start site of the LMO1 oncogene in primary samples from patients with T-cell acute lymphoblastic leukaemia." (PMID 28260788, 2017). "Accumulating evidence suggests that LMO1 and LMO2 act as oncogenic proteins in T-cell acute lymphoblastic leukemia, whereas LMO4 has recently been implicated in the genesis of breast cancer." (PMID 16420690, 2006). "LMO1, LMO2 and LMO3 express specificity in different cells of the adult mammalian central nervous system, and LMO1 and LMO2 act as oncogenes in acute T-cell lymphoblastic leukemia." (PMID 25829251, 2015).
breast carcinoma (7 papers, 2005 to 2025). "Notably, LMO1 and PRAME were strongly upregulated in the resistant cells, further highlighting their strong association with aggressive breast cancer phenotypes." (PMID 40076569, 2025). "LMO1 and LMO2 overexpression is linked to T-cell tumourigenesis and LMO4 has been associated with breast oncogenesis, where overexpression is observed in approximately 50% of breast cancer cell lines and primary breast cancers." (PMID 16280053, 2005).
lung carcinoma (6 papers, 2016 to 2024). "In order to identify the mechanisms underlying the oncogenic function of LMO1 and its direct clinical relevance, we exploited clinical data from lung cancer patients." (PMID 30038707, 2018). "Altogether, our results suggest that LMO1 expression is an independent determinant of lung cancer progression and prognosis at least in specific subgroups of patients." (PMID 30038707, 2018). "Together, these results indicate that LMO1 functions to promote survival and proliferation of lung cancer cells." (PMID 30038707, 2018). "By combining gene expression correlations with patient survival and functional in vitro investigations, we further identified TTK as mediating the oncogenic function of LMO1 in lung cancer cells." (PMID 30038707, 2018). "Together, these results support a role for TTK in mediating the function of LMO1 in lung cancer cells." (PMID 30038707, 2018). "Further studies in genetic mouse models with larger sample sizes are certainly needed in order to fully understand the role of LMO1 in lung cancer tumorigenesis." (PMID 30038707, 2018). "We showed for the first time that LMO1 has the general property of promoting cell proliferation in lung cancer cells representing different histological subtypes." (PMID 30038707, 2018). "We also investigated the tumorigenic function of LMO1 in vivo in a mouse lung cancer xenograft model generated using H1993 cells." (PMID 30038707, 2018). "To further characterize the growth-promoting function of LMO1 in lung cancer cells, we examined the effect of LMO1 over-expression in H358 cells, a lung cancer cell line with low endogenous levels of LMO1 mRNA." (PMID 30038707, 2018). "Coupled with our in vitro findings that LMO1 functions to promote growth of lung cancer cells, our results support LMO1 expression as a functional oncogenic and prognostic biomarker for neuroendocrine differentiation of NSCLC." (PMID 30038707, 2018). "Our analyses identified six candidate genes that are significantly correlated with LMO1 expression, significantly up-regulated in lung cancer specimens and significantly correlated with poor patient survival." (PMID 30038707, 2018). "In this study, we identified LMO1 as a potential biomarker of neuroendocrine differentiation of lung cancer." (PMID 30038707, 2018). "Taken together, these results suggest that TTK plays a key role in mediating the oncogenic function of LMO1 in lung cancer cells." (PMID 30038707, 2018). "To compare the effect of LMO1 depletion on survival of lung cancer cells to that of normal lung cells, we transfected increasing doses of siLMO1 and assessed survival of lung cancer line H1993 and immortalized normal HBEC cells." (PMID 30038707, 2018). "We discovered a correlation between LMO1 expression and both neuroendocrine differentiation and lung cancer patient survival." (PMID 30038707, 2018). "We also explored the mechanisms of LMO1 action in lung cancer cells by combining clinical data analysis and in vitro functional investigation." (PMID 30038707, 2018). "We provide the first identification that TTK acts as a downstream mediator of LMO1 function in lung cancer cells." (PMID 30038707, 2018). "Over-expression of LMO1 with pcDNA3.1-Flag-LMO1 expression vector significantly up-regulated expression of TTK mRNA as compared with cells transfected with empty vector pcDNA3.1 in six of the seven lung cancer cell lines tested." (PMID 30038707, 2018). "Candidate genes identified as potentially mediating the function of LMO1 in lung cancer." (PMID 30038707, 2018). "Furthermore, LMO1 over-expression increased cell proliferation in 7 lung cancer cell lines with low or medium LMO1 mRNA levels, as measured by BrdU incorporation." (PMID 30038707, 2018). "This evidence points to an important role for LMO1 in the tumorigenesis of lung cancer." (PMID 30038707, 2018).
lung carcinoma (continued). "In order to directly identify candidate mediators that are relevant to both lung cancer tumorigenesis and patient survival, we began with genes displaying significant correlation with mRNA levels of LMO1 and neuroendocrine markers CHGA, SYP and ENO2 levels in the MDACC dataset." (PMID 30038707, 2018). "We next sought to determine the gene(s) that mediate the function of LMO1 in lung cancer." (PMID 30038707, 2018). "Overall, our work provides new insights into the function of LMO1 in lung cancer." (PMID 30038707, 2018). "To examine whether LMO1 has an effect on lung cancer cell survival, we knocked down LMO1 expression in a panel of lung cancer cell lines of different histological subtypes with different genetic backgrounds and various LMO1 mRNA expression levels." (PMID 30038707, 2018). "To further evaluate the association of LMO1 expression with neuroendocrine differentiation in lung cancer cells, we examined the correlation between LMO1 mRNA levels and mRNA levels of neuroendocrine markers, including chromogranin A (CHGA), synaptophysin (SYP) and neuron-specific enolase-2 (ENO2)." (PMID 30038707, 2018). "Our in vitro investigations indicated that LMO1 had the general property of promoting cell proliferation in lung cancer cells representing different histological subtypes, suggesting a general oncogenic function of LMO1 in lung cancer." (PMID 30038707, 2018). "Additionally, recent studies indicated that in the anti-EGFR therapy, overexpression of LMO1 may be a predictive marker for the colorectal cancer, lung cancer, and prostate cancer." (PMID 27009839, 2016). "Its expression is related to the neuroendocrine differentiation of lung cancer, and it is a determinant of lung cancer invasiveness and prognosis, and TTK mediates the carcinogenic effect of LMO1 in lung cancer cells." (PMID 35784389, 2022). "We demonstrated that LMO1 has a general cell growth-promoting function independent of the histological subtypes and genetic backgrounds of the lung cancer cells." (PMID 30038707, 2018). "In analyzing the expression of LMO1 across a panel of lung cell lines, we found that LMO1 expression levels were significantly and dramatically higher in SCLC cells, an aggressive neuroendocrine subtype of lung cancer, relative to NSCLC and normal lung cells." (PMID 30038707, 2018). "When analyzing the whole patient population in each of the two dataset, LMO1 mRNA level was not identified as an independent predictor of lung cancer patient survival." (PMID 30038707, 2018). "To examine the clinical relevance of LMO1 expression in lung cancers, we first assessed the correlation between LMO1 mRNA levels and patient survival by Kaplan-Meier analysis in a dataset of 245 NSCLC lung cancer patients collected at MD Anderson Cancer Center (MDACC)." (PMID 30038707, 2018). "However, the function of LMO1 in other histological subtypes of lung cancer, such as small cell lung cancer (SCLC), was not investigated." (PMID 30038707, 2018). "In addition to our findings on LMO1, we identified five genes (GNG4, NCAPG, SPC25, ASPM and KIF2C) that are expressed at higher levels in lung tumors relative to NATs and are significantly correlated with poor survival of lung cancer patients, suggesting possible oncogenic functions in lung cancer." (PMID 30038707, 2018).
gastric cancer (5 papers, 2020 to 2023). A primary or metastatic malignant neoplasm involving the stomach. "Hsa_circ_0021087 (thereafter named circLMO1) is a circRNA generated from the circularization of exon 2 and exon 3 of LIM Domain Only 1 (LMO1) and first identified as a tumor suppressor in gastric cancer." (PMID 35321435, 2022). "GSDMA is not only inhibited in esophageal cancer and gastric cancer cells, but it has been found that this mechanism can also induce cell death by upregulating the expression of GSDMA through the transcription factor LMO1." (PMID 37561524, 2023). "GSDMA was suppressed in esophageal and gastric cancer cells and TGF-b can upregulate GSDMA through the transcription factor LMO1 to induce cell death." (PMID 34778452, 2021).
T-cell leukemia (3 papers, 2018 to 2024). A malignant disease of the T-lymphocytes in the bone marrow, thymus, and/or blood. "LMO1 belongs to a large family of proteins that are required for many developmental processes and are implicated in the onset or the progression of several cancers, including T cell leukemia, breast cancer and neuroblastoma." (PMID 35563322, 2022).
glioblastoma (2 papers, 2022 to 2025). The most malignant astrocytic tumor (WHO grade IV). "The results also in the CGGA revealed that the glioblastoma patients receiving chemotherapy or radiotherapy in the high LMO1 expression group had a poorer prognosis than patients in the low LMO1 expression group." (PMID 35280742, 2022).
glioma (2 papers, 2017 to 2022). A benign or malignant brain and spinal cord tumor that arises from glial cells (astrocytes, oligodendrocytes, ependymal cells). "In conclusion, our study highlighted that increased LMO1 expression levels were associated with higher tumor grade and poor prognosis in human glioma." (PMID 35280742, 2022). "In view of the prognostic value of LMO1 in glioma, we constructed a nomogram and risk classification system for predicting 3- and 5-year survival." (PMID 35280742, 2022). "Besides the use of LMO1 as a novel prognostic biomarker of glioma, underlying mechanisms of LMO1 were identified." (PMID 35280742, 2022). "The data revealed that the expression of LMO1 mRNA in human gliomas was correlated with 1p/19q co-deletion and MGMT promoter methylation status but not IDH status." (PMID 35280742, 2022). "Regarding biological function, LMO1 facilitated the proliferation, invasion and migration of glioma cells by activation of NF-kB pathway." (PMID 35280742, 2022). "To investigate the further relationship between LMO1 expression and clinical prognosis, we collected survival data from 42 patients with different grades of glioma." (PMID 35280742, 2022). "Of note, high expression of LMO1 in the nuclei of tumor cells was observed in great part of the patients with glioma by IHC." (PMID 35280742, 2022). "Our data suggested that LMO1, as a novel biomarker of gliomas, plays an important role in gliomas though the NF-κB signaling pathway." (PMID 35280742, 2022). "Based on our data, we propose that LMO1 is a novel biomarker of human glioma cells that promote growth and migration by activating NF-kB signaling pathway." (PMID 35280742, 2022). "The results display that elevated LMO1 expression was clinically correlated with unfavorable outcomes of glioma patients." (PMID 35280742, 2022). "Taken together, these results demonstrate that LMO1 is an upstream factor modulating the NF-kB pathway in glioma." (PMID 35280742, 2022). "By ICH analysis, we also found that the accumulation of LMO1 protein is significantly positively correlated with p-p65 expression (n =37; p=0.0064) in human glioma." (PMID 35280742, 2022). "Considering the clinical factors of glioma, these parameters (LMO1 and NGFR expression level, age, gender, WHO grade, IDH status and 1p/19q co-deletion) were included in the predictive model." (PMID 35280742, 2022). "The present study first focused on detecting the expression level of LMO1 in normal brain tissue and tumor tissue obtained from patients with glioma by mRNA level in TCGA, CGGA and GEO dataset." (PMID 35280742, 2022). "Correspondingly, the expression of the LMO1 protein was higher in human gliomas (WHO IV, n = 31; WHO II-III, n = 6) than in normal brain tissues (n = 5)." (PMID 35280742, 2022). "This study provides new insights and evidences that high level expression of LMO1 is significantly correlated with progression and prognosis in human gliomas." (PMID 35280742, 2022). "The results demonstrated that elevated LMO1 expression was clinically correlated with unfavorable outcomes of glioma patients outcome." (PMID 35280742, 2022). "Collectively, these in vivo and in vitro experiments revealed that LMO1 is essential for proliferation and invasion of glioma cells in vivo." (PMID 35280742, 2022). "To understand the function of LMO1 in glioma development, we investigated the expression level of LMO1 in multiple datasets." (PMID 35280742, 2022). "The impact of LMO1 on glioma cells proliferation in vitro was then examined." (PMID 35280742, 2022). "It was observed that expression of LMO1 was significantly higher in high-compared to low-grade gliomas, and may serve as an independent prognostic factor for gliomas." (PMID 35280742, 2022). "Clearly, LMO1 protein were mainly localized in the nuclear of glioma cells." (PMID 35280742, 2022). "Taken together, these data revealed that NGFR, which was upregulated by LMO1 in glioma, may induce poor prognosis." (PMID 35280742, 2022).